EIF3B (eukaryotic translation initiation factor 3 subunit B)
Diseases named in the same sentence as EIF3B in open-access papers (continued):
Sharing a sentence is not in itself a finding about the gene and the disease.
non-small cell lung carcinoma (6 papers, 2020 to 2022). A group of at least three distinct histological types of lung cancer, including non-small cell squamous cell carcinoma, adenocarcinoma, and large cell carcinoma. "Moreover, METTL3 induces non-small cell lung cancer (NSCLC) drug resistance and metastasis by promoting Yes-associated protein (YAP) mRNA translation via a m6A -YTHDF1/3/eIF3b-dependent mechanism." (PMID 33015074, 2020). "METTL3 relies on YTHDF1/3 and eIF3B to promote yes-associated protein (YAP) mRNA translation and increases YAP mRNA stability by modulating the MALAT1–miR-1914-3p–YAP axis, thereby inducing treatment resistance and metastasis in non-small cell lung cancer (NSCLC)." (PMID 32398132, 2020). "METTL3 promoted yes-associated protein (YAP) mRNA translation through YTHDF1/3 and eIF3B, and increased the stability of YAP mRNA by regulating the MALAT1/miR-1914-3p/YAP axis to induce non-small cell lung cancer (NSCLC) treatment metastasis and resistance b." (PMID 35711459, 2022).
osteosarcoma (6 papers, 2019 to 2022). A usually aggressive malignant bone-forming mesenchymal neoplasm, predominantly affecting adolescents and young adults. "Several studies have demonstrated that overexpressed eIF3b could promote the progression of malignant cancers such as glioblastoma cells,colon cancer, osteosarcoma and lung cancer." (PMID 31481019, 2019). "In addition to U2OS osteosarcoma cells, CisPt potently induces G3BP1-positive, eIF4g and eIF3b- negative foci in other cancer cell lines (including HeLa (cervix), MES-SA (uterus) and SiHa (cervix)) under similar doses." (PMID 34864307, 2022).
colon cancer (5 papers, 2012 to 2024). "Previous studies showed that EIF3B was abundantly expressed in colon cancer tissues, and the silencing of EIF3B inhibited the proliferation of colon cancer cells." (PMID 33996561, 2021). "In our study, using the RNA interference with lentivirus vector containing the EIF3B gene, we knocked down the expression of EIF3B gene in the colon cancer cell strain SW1116." (PMID 22734884, 2012). "We performed RNA interference (RNAi) with the lentivirus vector system to silence the EIF3B gene using the colon cancer cell strain SW1116." (PMID 22734884, 2012). "The results of the semi-quantitative PCR, which set GAPDH as an internal reference, showed that EIF3B gene was abundantly expressed in colon cancer cell SW1116." (PMID 22734884, 2012). "This research was carried out by constructing a lentiviral vector containing RNA interference expression cassettes of EIF3B gene and introducing it into the colon cancer cell strain SW1116 to analyze the effect of EIF3B gene silencing on the proliferation of colon cancer cells." (PMID 22734884, 2012). "The silencing of EIF3B gene expression inhibits the proliferation of colon cancer cells." (PMID 22734884, 2012). "Downregulation of EIF3B gene expression inhibited the proliferation of colon cancer cells." (PMID 22734884, 2012). "As subunits in the eIF3(a:b:i:g) subcomplex, only eIF3a and eIF3i, but not eIF3b and eIF3g, are overexpressed in human colon cancers compared with their matching normal tissues." (PMID 39413959, 2024).
esophageal squamous cell carcinoma (5 papers, 2019 to 2024). Esophageal squamous cell carcinoma (ESCC) is a type of esophageal carcinoma (EC) that can affect any part of the esophagus, but is usually located in the upper or middle third. "Elevated levels of EIF3B have been linked to poor prognosis in clear cell renal cell carcinoma, esophageal squamous cell carcinoma, gastric cancer, and bladder cancer." (PMID 38687509, 2024).
glioblastoma (5 papers, 2016 to 2024). The most malignant astrocytic tumor (WHO grade IV). "M6A methylation can regulate the apoptosis of glioma cells, and Liang’s study showed that eIF3B was upregulated in the glioblastoma cell line U87." (PMID 35688823, 2022). "In addition, EIF3B promoted the proliferation of glioblastoma tumor cells and might be related to the development of human glioblastoma." (PMID 33996561, 2021).
melanoma (5 papers, 2022 to 2024). A malignant, usually aggressive tumor composed of atypical, neoplastic melanocytes. "To explore EIF3B-associated biological functions in melanoma, we performed GSVA using TCGA-SKCM dataset." (PMID 35273605, 2022). "Second, the signaling pathways and molecular mechanisms underlying the role of EIF3B in the regulation of melanoma progression demand further elucidation." (PMID 35273605, 2022). "Thus, a copy-number gain of EIF3B may be associated with resistance to anti-PD-1 therapy in melanoma through β-catenin activation." (PMID 35013211, 2022). "To summarize, we established a prognostic model for melanoma and identified the role of EIF3B in melanoma progression and immunotherapy resistance development." (PMID 35273605, 2022). "Further, we verified the potential role of EIF3B in the OS of patients with melanoma and response to immunotherapy." (PMID 35273605, 2022). "We then performed submap analyses to evaluate the response of melanoma patients with high and low EIF3B expression to anti-PD-1 immunotherapy." (PMID 35273605, 2022). "In vitro models revealed that EIF3B knockdown inhibited melanoma cell migration and invasion, and decreased TGF-β1 level in supernatant compared with si-NC cells." (PMID 35273605, 2022). "Our in vitro experiments revealed that EIF3B knockdown significantly inhibited the migration and invasion of melanoma cells." (PMID 35273605, 2022). "EIF3B knockdown also inhibited the migration and invasion of melanoma cells in vitro, and decreased concentration of TGF-β1 in supernatant." (PMID 35273605, 2022). "We believe that our ulcer-immunity related prognostic model can widen our understanding of the biology of melanoma and prognosis prediction and that EIF3B can act as a promising therapeutic drug target in melanoma treatment." (PMID 35273605, 2022). "The inhibition of PTGS2 could suppress the cell proliferation and migration in malignant melanoma by overexpression of eukaryotic translation initiation factor 3 subunit B." (PMID 38643459, 2024). "Moreover, an earlier study verified that EIF3B, as a key gene of the subtype of melanoma with the worst prognosis, has the ability of inducing immune-depletion and reducing CD8+ T-cell infiltration." (PMID 38400862, 2024). "EIF3B was then identified as the hub gene of the subtype related with the worst prognosis in melanoma, which provided a clue that EIF3B could be a potential therapeutic drug target in melanoma." (PMID 35273605, 2022). "Our prognostic model could provide meaningful prognostic value in clinical application, and our findings also highlight the potential role of EIF3B in melanoma progression." (PMID 35273605, 2022). "Finally, the relationship between EIF3B and its immunosuppressive role in melanoma needs to be further studied in in vivo models." (PMID 35273605, 2022). "Based on these finding, we believe that EIF3B plays a key role in the immune response in melanoma." (PMID 35273605, 2022). "This prompted us to further investigate the role of EIF3B in melanoma progression." (PMID 35273605, 2022).
pancreatic cancer (5 papers, 2020 to 2024). "Splicing factors (SRSF1, EIF3B, TIA1) are implicated in the enrichment of pancreatic cancer-derived exosomal miRNA, particularly contributing to the exosome shuttling of miR-1246." (PMID 38419074, 2024). "The expression of EIF3B in pancreatic cancer tissues and para-carcinoma tissues revealed in immunohistochemistry analysis." (PMID 33996561, 2021). "Relationship between EIF3B expression and tumor grade in patients with pancreatic cancer." (PMID 33996561, 2021). "Relationship between EIF3B expression and tumor characteristics in patients with pancreatic cancer." (PMID 33996561, 2021). "Using a labeled miR-1246 probe as “bait”, we fished out several RBPs from pancreatic cancer cells, including serine and arginine rich splicing factor 1 (SRSF1), eukaryotic translation initiation factor 3 subunit B (eIF3B), and T cell-restricted intracellular antigen 1 (TIA1)." (PMID 32819370, 2020).
asthma (3 papers, 2021 to 2025). "Besides, it was found that the eosinophils which are very important for severe asthma were affected by YTHDF3 and EIF3B." (PMID 34647423, 2021).
breast carcinoma (3 papers, 2021 to 2024). "The association between the alteration of EIF3B and breast cancer prognosis was also examined." (PMID 35040374, 2022). "Furthermore, high expression and mutation of EIF3B were positively associated with poor prognosis in breast cancers." (PMID 35040374, 2022). "Collectively, our results suggested EIF3B as a potential prognostic marker and therapeutic target for breast cancer." (PMID 35040374, 2022). "We also confirmed that EIF3B was more highly expressed in breast cancer cells and tissues than normal and correlated with a worse outcome." (PMID 35040374, 2022). "Our bioinformatics research and experimental results both revealed that the expression of EIF3B was higher in breast cancer cells and tissues than in normal." (PMID 35040374, 2022). "Based on our results, EIF3B was chosen as a more meaningful molecular target for further research in breast cancer." (PMID 35040374, 2022). "The EIF3B protein expression pattern in breast cancer tissues and adjacent normal breast tissues was tested by IHC." (PMID 35040374, 2022). "We also identified the crucial role of EIF3B in breast cancer progression by regulating the cell cycle and proliferation." (PMID 35040374, 2022). "The results confirmed that the upregulated EIF3B in breast cancer cells and tissues was highly correlated with advanced pathologic stages and poor survival." (PMID 35040374, 2022). "To explore the function and related pathways of EIF3B, we conducted a correlation analysis of EIF3B and other genes in breast cancer using TCGA data." (PMID 35040374, 2022). "Combined with experimental verification, we also confirmed the crucial function of EIF3B in breast cancer." (PMID 35040374, 2022). "Meanwhile, we performed the immunohistochemical assay, real-time RT-PCR, and Western blotting to analyze EIF3B expression levels in breast cancer." (PMID 35040374, 2022). "Therefore, the results confirmed that the higher EFI3B mutation leads to a poor prognosis of breast cancer, and the mutation-related genes were associated with important physiological processes, which may explain the reason why the increased EIF3B leads to tumorigenesis." (PMID 35040374, 2022). "Here, the results suggested that only EIF3B as a prognostic biomarker was significantly related to poor survival of breast cancer." (PMID 35040374, 2022). "Furthermore, EIF3B was selected for mutation analysis and experimental verification also suggested the important role of EIF3B in affecting breast cancer progression through cell cycle regulation." (PMID 35040374, 2022). "Thus, we selected the EIF3B subunit to identify the frequency of genetic alterations in EFI3B among breast cancer patients using the cBioPortal database." (PMID 35040374, 2022). "However, very little was found in the literature on the detailed function of EIF3B in breast cancer." (PMID 35040374, 2022). "And EIF3B was selected for investigating the role in the diagnosis of breast cancer." (PMID 35040374, 2022). "EIF3B maybe a novel biomarker for breast cancer diagnosis and prognosis." (PMID 35040374, 2022). "Therefore, a possible explanation for the role of EIF3B in regulating breast cancer might be that it affects the expression of MCM7 to block the G1/S transition of the breast cancer cell cycle and cell proliferation." (PMID 35040374, 2022). "Interestingly, the expression of MCM7 decreased after the knockdown of EIF3B expression, indicating that EIF3B might inhibit breast cancer cell growth by inhibiting the G1/S transition of the cell cycle." (PMID 35040374, 2022). "Consistent with the results of GEPIA and TCGA, it indicated significantly higher EIF3B expression and lower EIF3D/ F/ L in breast cancer tissues." (PMID 35040374, 2022). "Consistently, the mRNA expression of EIF3B was positively related to tumor stage, SBR, and NPI grade in breast cancer." (PMID 35040374, 2022).
breast carcinoma (continued). "A higher mutation of EIF3B was accompanied by worse DFS (P < 0.05) and RFS (P < 0.01) in breast cancer, while the OS showed no significance." (PMID 35040374, 2022).
hepatocellular carcinoma (3 papers, 2020 to 2022). A malignant tumor that arises from hepatocytes. "Gene function enrichment analysis revealed that EIF3B is involved in the regulatory pathway and overexpressed in patients with hepatoma." (PMID 33142921, 2020). "RP11-284P20.2 promotes cell proliferation and invasion in hepatocellular carcinoma by recruiting EIF3b to induce c-met protein synthesis." (PMID 32100822, 2020). "In addition, the translation facilitated by METTL16, which is important in the carcinogenesis of hepatocellular carcinoma, is mediated by the interaction between METTL16 and EIF3A and EIF3B." (PMID 36051357, 2022).
liver cancer (3 papers, 2021 to 2024). An epithelial or non-epithelial malignant neoplasm that arises from the liver. "Another study found that eIF3b was highly expressed in liver cancer tissues and had promising diagnostic and prognostic value." (PMID 34692544, 2021). "YTHDF2 can also promote immune evasion and angiogenesis in liver cancer by recognizing the m6A modification site in the 5’UTR of ETS variant transcription factor 5 mRNA and recruiting the eukaryotic translation initiation factor 3 subunit B to facilitate its translation." (PMID 39593172, 2024).
lung carcinoma (3 papers, 2015 to 2022). "Two lung cancer-associated mutations in eIF3b and eIF3c that have been tested in course of this study also had the capacity to reverse the reduced size phenotype, indicating that both mutations do not represent loss-of-function mutants of the eIF3-complex." (PMID 26172298, 2015). "To provide additional support for this model, we sought to determine the relevance of lung carcinoma-associated single base pair mutations identified in eIF3b and eIF3c genes." (PMID 26172298, 2015). "To this end, we used the Catalogue of somatic mutations in cancer (COSMIC) library to derive two - yet uncharacterized - single base pair somatic mutations in eIF3b and eIF3c that have been confirmed in lung carcinoma." (PMID 26172298, 2015).
bladder cancer (2 papers, 2015 to 2024). "Depletion of eIF3b has previously been shown to strongly decrease the levels of S-phase and G2/M-phase cyclins (cyclin A and cyclin E) in a bladder cancer cell line." (PMID 26172298, 2015).
liver fibrosis (2 papers, 2021 to 2025). "The combination of piR-823 and EIF3B-mediated TGF-1β expression in HSC promotes liver fibrosis and cirrhosis." (PMID 39102033, 2025). "In particular, EIF3B is a translation promoter of TGF-β1, which is a well-recognized factor in the pathogenesis of liver fibrosis; therefore, the interaction between piR-823 and EIF3B can induce a higher TGF-β1 expression that leads to greater activation of HSCs to initiate liver fibrosis." (PMID 35008366, 2021). "Likewise, piR-823 binds to eukaryotic initiation factor 3 B (EIF3B) and upregulates the expression of transforming growth factor-1beta (TGF-1β) to initiate hepatic stellate cells during hepatic fibrosis." (PMID 39102033, 2025).
malaria (2 papers, 2016 to 2021). Malaria is a serious and sometimes fatal disease caused by a parasite that commonly infects a certain type of mosquito which feeds on humans. "Besides, the other identified key gene, PSMF1 and EIF3B, have also been reported associated with malaria in previous studies." (PMID 33942992, 2021). "Within the nine genes, five genes (MBP, SAMSN1, PSMF1, SLC39A8, and EIF3B) were previously found to be involved in malaria, and the remaining four genes (SMPDL3A, FABP5, SPSB3, and SHARPIN) were identified for the first time in the current study." (PMID 33942992, 2021). "Conversely, the other five key genes (MBP, SPSB3, PSMF1, SHARPIN, and EIF3B) were negatively correlated with malaria severity and decreased in CM." (PMID 33942992, 2021). "SAMSN1, SLC39A8, SMPDL3A, and FABP5 were positively correlated with malaria phenotype/severity and showed an upregulation in the CM group compared with healthy controls, while MBP, SPSB3, PSMF1, SHARPIN, EIF3B were negatively correlated with malaria severity and downregulated in the DEG." (PMID 33942992, 2021).
ovarian carcinoma (2 papers, 2022 to 2023). A malignant neoplasm originating from the surface ovarian epithelium. "It has been reported that inhibition of EIF3B expression could significantly inhibit proliferation and increase apoptosis of ovarian cancer cells." (PMID 37749641, 2023).
astrocytomas (1 paper, 2021). "We showed that the expression of eIF3B, eIF3I, eIF4A1, eIF4H and eIF6 was significantly increased in astrocytomas, in particular in GBM, for protein and mRNA levels." (PMID 33807050, 2021).
benign adenoma (1 paper, 2024). "Additionally, the expression of both eIF3a and eIF3i but not eIF3b and eIF3g is also increased in benign adenoma polyps." (PMID 39413959, 2024).
breast tumors (1 paper, 2020). "In addition, several “non-core” subunits (eIF3b, d, e and f) correlated strongly with the tumorigenesis of breast neoplasm." (PMID 32368187, 2020).